CD36 (CD36 molecule (CD36 blood group))
Diseases named in the same sentence as CD36 in open-access papers (continued):
Sharing a sentence is not in itself a finding about the gene and the disease.
dermatomyositis (1 paper, 2014). Dermatomyositis (DM) is a type of idiopathic inflammatory myopathy characterized by evocative skin lesions and symmetrical proximal muscle weakness. "TSP-1, CD36, and CD47 expression have been reported to be upregulated in inclusion body myositis and dermatomyositis muscle specimens." (PMID 25501558, 2014).
dilation (1 paper, 2014). "In the absence of ventricular dilation and dysfunction, 12-month-old HCM females did not exhibit reduced CD36 expression or increased circulating TG." (PMID 24567073, 2014).
dimethylglycine dehydrogenase deficiency (1 paper, 2023). An extremely rare autosomal recessive glycine metabolism disorder characterized clinically in the single reported case to date by muscle fatigue and a fish-like odor. "However, the GCR of DMGDH, CD36 and GJB2, the variants on which were linked to diseases Dimethylglycine dehydrogenase deficiency, Platelet glycoprotein IV deficiency, and Deafness (autosomal recessive 1A), respectively, exhibited substantial variations across ethnic groups." (PMID 37985665, 2023).
E. coli infection (1 paper, 2018). "To understand the mechanism underlying the differential effects of E. coli infection on liver and blood triglyceride contents of Mkp-1+/+ and Mkp-1−/− mice, we measured Cd36 levels by qRT-PCR." (PMID 30563203, 2018). "Liver Cd36 mRNA levels were similar between control Mkp-1+/+ and Mkp-1−/− mice, and E. coli infection caused a significant increase in Cd36 mRNA levels in Mkp-1+/+ mice but had little effect on Cd36 mRNA levels in Mkp-1−/− mice." (PMID 30563203, 2018). "Interestingly, in Mkp-1+/+ mice E. coli infection resulted in downregulation of genes that facilitate fatty acid synthesis but upregulation of Cd36 and Dgat2, whose protein products mediate fatty acid uptake and triglyceride synthesis, respectively." (PMID 30563203, 2018). "Finally, mRNA expression of Cd36, the liver protein mediating fatty acid uptake, is markedly upregulated in Mkp-1+/+ mice after E. coli infection." (PMID 30563203, 2018).
Encephalopathy (1 paper, 2021). Encephalopathy is a term that means brain disease, damage, or malfunction. "Bezafibrate, a pan-PPAR agonist, can significantly increase the levels of CD36, ACOX1, CPTI, CPT II, and uncoupling protein-2/3 (UCP-2/3), improve mitochondrial ΔΨm, restore intracellular ATP level, and further improve IAV-associated encephalopathy." (PMID 34540999, 2021).
endotoxemia (1 paper, 2016). "Adhesion of iRBCs to CD36 and ICAM-1 as well as rosetting was similar in children with or without endotoxemia." (PMID 26830671, 2016).
esophageal carcinomas (1 paper, 2023). A primary or metastatic malignant neoplasm involving the esophagus. "We confirmed a significantly lower level of stromal CD36 expression by immunohistochemical (IHC) analysis of breast, lung, colon, and esophageal carcinomas compared to DF tissues." (PMID 37816052, 2023).
experimental autoimmune encephalomyelitis (1 paper, 2020). An autoimmune demyelinating disease of the central nervous system that is produced experimentally in animals by the injection of homogenized brain or spinal cord in Freund's adjuvant. "Finally, the experimental autoimmune encephalomyelitis (EAE) model was used to establish the impact of CD36 inhibition on neuroinflammation and myelin phagocytosis in vivo." (PMID 32718316, 2020). "Also, within demyelinating lesions in the experimental autoimmune encephalomyelitis (EAE) mouse model, foamy IBA1-expressing phagocytes highly expressed CD36." (PMID 32718316, 2020).
fungal infections (1 paper, 2024). "Consequently, CD36 emerges not only as a promising biomarker for C. albicans infection but also as a potential target for therapeutic intervention in fungal infections and associated inflammatory responses." (PMID 38926392, 2024).
gastric disease (1 paper, 2021). "The authors find mucosal repair is abrogated due to defective epithelial cell renewal and progenitor cell differentiation, due to reduced fatty acid delivery and altered lipid metabolism, and find associations between low CD36 expression and gastric diseases." (PMID 34728772, 2021). "We also identify genetic associations in two large patient databases between the CD36 expression and gastric disease." (PMID 34728772, 2021).
Gaucher disease (1 paper, 2021). Gaucher disease (GD) is a lysosomal storage disorder encompassing three main forms (types 1, 2 and 3), a fetal form and a variant with cardiac involvement (Gaucher disease - ophthalmoplegia - cardiovascular calcification or Gaucher-like disease). "What is the implication of CD36 in the uptake of lipids and autophagy in the metabolic tissues of NPC and Gaucher diseases?" (PMID 34957117, 2021). "Overall, alterations in the expression or function of CD36 have not been reported in adipocytes in NPC or in Gaucher disease." (PMID 34957117, 2021). "Thus, it is possible to speculate that CD36 could participate in the modulation of lysosomal dysfunction in NPC and Gaucher diseases." (PMID 34957117, 2021).
glaucoma (1 paper, 2022). Increased pressure in the eyeball due to obstruction of the outflow of aqueous humor. "Therefore, inhibition of CD36-mediated amyloid Aβ accumulation in the retina can effectively prevent RGC loss, which may provide A new idea for the treatment of glaucoma." (PMID 36611964, 2022).
glomerulopathies (1 paper, 2022). "CD36 is involved in podocyte injury in several glomerulopathies and was reported to be a vital candidate gene in LN." (PMID 35999224, 2022). "It has been reported that CD36 can activate the NLRP3 inflammasome contributing to the podocyte injury in obesity-related glomerulopathy and primary nephrotic syndrome." (PMID 35999224, 2022).
Hepatomegaly (1 paper, 2022). Abnormally increased size of the liver. "Analyses revealed that higher percentages of EMAP II+CD36+ cells were positively correlated with hepatomegaly, splenomegaly, and an advanced (intermediate and high risk) NHL stage." (PMID 36132984, 2022).
hereditary gingival fibromatosis (1 paper, 2024). Hereditary gingival fibromatosis (HGF) is a rare benign, slowly progressive, non-inflammatory fibrous hyperplasia of the maxillary and mandibular gingivae that generally occurs with the eruption of the permanent (or more rarely the primary) dentition or even at birth. "To date, genetic variants in five genes, SOS1, REST, ZNF862, ALK, and CD36, have been linked to hereditary gingival fibromatosis." (PMID 39201553, 2024).
hereditary hypertrophic cardiomyopathy (1 paper, 2011). "FAT/CD36 deficiency has been identified in some patients with hereditary hypertrophic cardiomyopathy, associated with a decreased myocardial uptake of fatty acids, suggesting that fatty acid transport and metabolism may be intricately linked to cardiac pathology." (PMID 22028857, 2011).
Hypercalcemia (1 paper, 2024). An abnormally increased calcium concentration in the blood. "This research has emphasized that suppressing CD36 or CD47 mitigates osteoclast formation, thereby inhibiting PTH-induced hypercalcemia in mouse models." (PMID 38167957, 2024).
Hypocalcemia (1 paper, 2019). An abnormally decreased calcium concentration in the blood. "Besides, a number of germline mutations in genes related to calcium metabolism (CACNA2D4, CD36, etc.)and the administration of irinotecan were speculated to be the causes of severe hypocalcemia." (PMID 31510946, 2019).
ileitis (1 paper, 2017). "For example, gene networks associated with ileitis were suppressed ~8% (P < 0.05), and included Cd36, Il4, Cd44, Cd4, and Cd40." (PMID 28446880, 2017).
Infectious skin diseases (1 paper, 2025). "Infectious skin diseases are associated with CD36 expression." (PMID 40565366, 2025).
intestinal tumors (1 paper, 2020). "In agreement with in vitro data, the analysis of intestinal tumors from mice with hetero- and homozygous deletions of FASN on C57BL/6-Apc/Cre background showed that deletion of FASN significantly upregulates CD36 expression." (PMID 32850342, 2020).
invasive lobular carcinoma (1 paper, 2014). "Moreover, the co-distribution of TSP-1 and CD36 in a subpopulation of invasive lobular carcinoma correlates with the capability of these cells to invade through surrounding stroma." (PMID 26273699, 2014).
iron deficiency (1 paper, 2021). "Yet, the expression of the CD36 surface marker, a key fatty acid translocase shown to selectively identify matured and mitochondria-rich hiPSC-CMs, was down regulated in iron deficiency." (PMID 35050131, 2021).
ischemic cardiomyopathy (1 paper, 2020). Ischemic cardiomyopathy is a cardiomyopathy in which a weakness in the muscle of the heart due to inadequate oxygen delivery to the myocardium with coronary artery disease being the most common cause. "The potential for ligands based on the GHRP-6 structure to target ischemic cardiomyopathy was however limited due to their lack of receptor selectivity, binding to both CD36 and the growth hormone secretagogue receptor (so-called ghrelin receptor, GHS-R1a)." (PMID 32717955, 2020).
ischemic disease (1 paper, 2018). Lack of blood supply to an area of the body, resulting in impairment of tissue oxygenation. "The conception of azasulfurylpeptide 3c has thus provided valuable insight into the structural relationships and useful tools for governing CD36 activity that could find their application in the treatment of inflammation underlying ischemic diseases." (PMID 30360354, 2018).
Kawasaki disease (1 paper, 2022). A rare inflammatory disease characterized by an acute febrile, systemic, self-limiting, medium-vessel vasculitis primarily affecting children. "Further studies are needed to clarify the possible mechanistic link between CD36 and the development of Kawasaki disease." (PMID 35154107, 2022).
kidney (1 paper, 2019). "Regrettably, as most reports on the relationship between CD36 and kidney diseases are about the disorders of kidney in metabolic diseases, there is no study about the role CD36 plays in immune response, which is worthy of further study in LN." (PMID 31592160, 2019).
kidney cancer (1 paper, 2024). Primary or metastatic malignant neoplasm involving the kidney. "Among the 13 different indications we examined, over 75% of patients with stage IV disease had high CD36 levels in all indications except Kidney cancer (65%)." (PMID 39627379, 2024). "When considering patients that were high for both CD36 and CD47, 11 out of 13 indications had more than 47% of cases with dual high levels of CD36/CD47, with Kidney Cancer (37%) and HCC (35%) as the exception." (PMID 39627379, 2024). "Finally, some indications, such as Kidney cancer and Melanoma, had no distinct pattern of CD36/CD47 expression levels across different disease stages." (PMID 39627379, 2024).
limb ischemia (1 paper, 2024). A ischemia that involves the limb. "Targeting CD36 was shown to offer promise for curtailing tissue injury following hind limb ischemia‐reperfusion." (PMID 39552437, 2024).
Listeria monocytogenes infection (1 paper, 2025). "Similarly, in Listeria monocytogenes infection, TIM3 expression in macrophages limits the phagocytosis of bacteria through interactions with the transcription factor nuclear factor NRF2 and the down-regulation of CD36 and the heme oxygenase 1-IL1β pathway." (PMID 41307843, 2025).
liver failure (1 paper, 2022). A liver disease characterized by the liver losing or has lost all of its function. "However, platelets and monocyte CD36 expression were lower in HBV-LC patients with liver failure compared with those without." (PMID 36406414, 2022).
lymphedema (1 paper, 2023). Excess fluid collection in tissues, causing swelling. "Lymphedema samples exhibited aberrant expression of metalloproteinases such as ADAMTSL1 and a decrease in transcripts associated with adipocyte identity (FABP4, CD36)." (PMID 38131378, 2023).
lymphopenia (1 paper, 2024). Reduction in the number of lymphocytes. "Notably, patients with lymphopenia demonstrated higher CD36 expression." (PMID 39266539, 2024).
malnutrition (1 paper, 2015). Inadequate nutrition resulting from poor diet, malabsorption, or abnormal nutrient distribution. "CD36−/− pups do not die due to malnutrition or dehydration since initiation of suckling is dependent on variable blends of maternal “signature odors” that are learned and recognized prior to first suckling, but not single odor cues such as oleic acid." (PMID 26441537, 2015).
mantle cell lymphoma (1 paper, 2023). Mantle cell lymphoma is a rare form of malignant non-Hodgkin lymphoma affecting B lymphocytes in the lymph nodes in a region called the ``mantle zone''. "Moreover, bortezomib-resistant mantle cell lymphoma cells were also found to exhibit elevated CD36 expression levels, increased FA uptake, and could similarly be re-sensitized to bortezomib with a function-blocking antibody of CD36." (PMID 37371076, 2023).
mastitis (1 paper, 2016). Inflammation of breast tissue during lactation or postpartum due to an obstructed duct or infection. "Surprisingly, CD36 mRNA levels were also significantly increased in E. coli-induced mastitis compared with healthy goats (P < 0.01)." (PMID 26976286, 2016). "The relationship between AP-1 and CD36 in E. coli-induced mastitis is an interesting finding." (PMID 26976286, 2016). "However, little is known about the effect of CD36 on downstream signaling pathways in mastitis because most studies have focused on the role of CD36 as a lipid transporter (FAT/CD36) and have neglected its role as a scavenger receptor in dairy ruminants." (PMID 26976286, 2016). "Interestingly, changes in CD36 mRNA expression were first revealed in E. coli mastitis." (PMID 26976286, 2016). "In E. coli-induced mastitis udders, the mRNA levels of TLR4 and CD36 were upregulated during the infection." (PMID 26976286, 2016). "The results indicated that E. coli-induced mastitis could trigger TLR4 and CD36 mRNA expression and activate the downstream signaling pathways in Xinong Saanen dairy goats." (PMID 26976286, 2016). "Additionally, this study indicates that CD36 plays a vital role in the LPS-induced activation of downstream signaling cascades and mediates E. coli phagocytosis via TLR4 in pGMECs, which offers a novel treatment strategy for mastitis." (PMID 26976286, 2016).
mesothelioma (1 paper, 2025). A usually malignant and aggressive neoplasm of the mesothelium which is often associated with exposure to asbestos. "Intriguingly, CD36 emerged as the predominantly expressed fatty acid transporter in both normal and mesothelioma cell lines." (PMID 40016284, 2025).
metastasis (1 paper, 2022). The spread or migration of cancer cells from one part of the body (where they first appeared) to another. "In addition, blockade of CD36 in MAMs restores CD8+T cell immunity and ameliorates liver metastasis in preclinical mouse models." (PMID 36184646, 2022).
mycobacterial infection (1 paper, 2023). "In mycobacterial infection, CD36 may participate in the entry of Mtb in adipocytes." (PMID 36909724, 2023). "Noteworthy, beyond TLR2 and CD36, blockade of CD14 and CD11b/CD18 also inhibited BCG-induced LDs biogenesis and the synthesis of lipid mediators, suggesting that in addition to CD36 other TLR2 co-receptors may regulate mycobacterial infection-triggered alterations in host lipid metabolism." (PMID 36909724, 2023).
Mycobacterium infection (1 paper, 2024). Infections with bacteria of the genus Mycobacterium. "Currently, an increasing number of studies have shown abnormal expression of CD36 in Mycobacterium infection, but the function of CD36 in Mycobacterium infection is still insufficient and ambiguous." (PMID 38881887, 2024).
Myocardial fibrosis (1 paper, 2021). "Downregulation of P4HA1 is involved in liraglutide-mitigated myocardial fibrosis through the CD36-JNK-AP1 pathway." (PMID 33981730, 2021).
Nagashima-type palmoplantar keratoderma (1 paper, 2022). "In addition, CD36 associated with platelet glycoprotein IV deficiency and SERPINB7 associated with Nagashima-type palmoplantar keratoderma have been unreported in China, and their prevalence is unclear." (PMID 36072675, 2022).
Opportunistic infection (1 paper, 2014). An infection that is caused by a pathogen that would generally not be able to cause an infection in a host with a normal immune system. "The present work shows that HIV-1 Nef protein may have a role in the strategies elaborated by HIV-1 to alter pathogen disease outcomes, by modulating CD36 expression in macrophages, favoring the onset of opportunistic infections in HIV-1 infected people." (PMID 24705461, 2014).
osteophytes (1 paper, 2016). "NCOR2 and CD36 genes were associated with induction of radiographic knee OA measured as either a K/L grading of ≥2.0 or the presence of osteophytes, while the polymorphisms at CILP, TNA, IL1RN and variation at inflmmatory genes appeared to correlate with radiographic progression over time." (PMID 27457563, 2016).
overnutrition (1 paper, 2019). An imbalanced nutritional status resulting from excessive intake of nutrients. "Our investigation of CD36, PPARγ, and mitochondrial DAMPs provides new insight into the crosstalk between metabolism and inflammation in the progression of overnutrition-caused liver fibrinogenesis." (PMID 31652636, 2019).
peripheral arterial disease (1 paper, 2022). A disorder of the arteries supplying the upper and lower extremity and the visceral organs. "Effect of CD36-blocking on tissue factor-triggered thrombin generation in platelet-rich plasma from 10 patients with the peripheral arterial disease (PAD) over time treated with aspirin (ASA) in the absence or presence of clopidogrel or low-dose rivaroxaban." (PMID 35600474, 2022).
peritonitis (1 paper, 2021). Inflammation of the peritoneum (tissue that lines the abdominal wall and covers most of the organs in the abdomen). "Moreover, rhEPO increased macrophage CD36 expression in WT mice during E. coli-induced peritonitis." (PMID 33927725, 2021).
placental insufficiency (1 paper, 2025). Failure of the placenta to deliver an adequate supply of nutrients and oxygen to the fetus. "Interestingly, in the present study, exposure to Intralipid upregulated fatty acid transporter (CD36 and CPT1) mRNA without changes to protein levels; this mismatch in mRNA and protein expression is also seen in placental insufficiency." (PMID 40420618, 2025).
podoconiosis (1 paper, 2024). A disease of the lymphatic vessels of the lower extremities that is caused by chronic exposure to irritant soils. "In line with this higher level of CD36 was observed in intermediate monocytes subsets of podoconiosis patients from the PBMC immunophenotyping in the current study." (PMID 38448477, 2024). "The expression of HLA-DR, CD40, CD86, and CD36 was analyzed on monocytes from 43 podoconiosis patients and 34 healthy controls." (PMID 38448477, 2024).
primary immunodeficiency (1 paper, 2023). "According to GSEA findings, the CD36 high expression group was highly enriched for primary immunodeficiency and viral protein interaction with cytokines and cytokine receptors." (PMID 36911691, 2023).
prostate tumor (1 paper, 2025). "Research indicates that CD36-mediated fatty acid uptake is essential for generating lipid oncogenic signals in prostate tumor tissues." (PMID 41179286, 2025).
protein deficiency (1 paper, 2021). "Moreover, in humans, common SNPs in the promotor of CD36 cause protein deficiency and have been associated with high levels of FAs and LDL in serum, a phenotype recapitulated in Cd36−/− mice." (PMID 35002769, 2021).